KANSL1L (KAT8 regulatory NSL complex subunit 1 like)
Synonyms: C2orf67; FLJ23861; FLJ32349; MSL1v2; KIAA1267L
Tractability: PROTAC: UniProt records ubiquitination sites on it; ubiquitination databases record sites on it.
Gene: Protein-coding gene on chromosome 2 (210,021,421 to 210,172,182, reverse strand). Ensembl gene ENSG00000144445.
Subcellular location (Human Protein Atlas): Cytosol
Gene Ontology:
Molecular function: histone acetyltransferase binding
Cellular component: NSL complex; H4 histone acetyltransferase complex; histone acetyltransferase complex
Genetic constraint (gnomAD): Loss-of-function variants: 14 observed, 64.2 expected, observed/expected ratio (o/e) 0.22, 90% interval 0.14 to 0.34. The upper end of that interval is the gene's LOEUF score, 0.34, which puts it in group 1 of 6, group 1 being the genes least tolerant of losing a copy. Missense variants: 802 observed, 822.34 expected, observed/expected ratio (o/e) 0.98, 90% interval 0.92 to 1.03. Synonymous variants: 293 observed, 289.58 expected, observed/expected ratio (o/e) 1.01, 90% interval 0.92 to 1.12.
Homologues: Orthologues: chimpanzee KANSL1L (99% identical), macaque KANSL1L (97% identical), dog KANSL1L (88% identical), pig KANSL1L (86% identical), rabbit KANSL1L (85% identical), rat Kansl1l (81% identical), guinea pig KANSL1L (77% identical), mouse Kansl1l (77% identical), tropical clawed frog kansl1l (33% identical), zebrafish kansl1l (21% identical), Drosophila melanogaster nsl1 (16% identical). Paralogues in human: KANSL1 (25% identical).
Diseases named in the same sentence as KANSL1L in open-access papers:
KANSL1L is named in the same sentence as 7 diseases in open-access papers, as found by Europe PMC text mining. Sharing a sentence is not in itself a finding about the gene and the disease. The quoted sentences say what the papers report.
Koolen-de Vries syndrome (1 paper, 2023). A chromosomal anomaly characterized by developmental delay, childhood hypotonia, facial dysmorphism, and a friendly/amiable behavior. "Overall, the Kansl1l data indicated many phenotypic similarities in organs, such as heart, kidney, testes, and eye, between the KO mouse and patients suffering from the rare monogenic Koolen-de Vries syndrome." (PMID 37160609, 2023).
cardiac disease (1 paper, 2018). "The remaining differentially expressed genes in MuRF1 Tg + hearts after CH exposure associated with alternative splicing (Ptpru, Svopl, Syt16, Ccp110, Jakmip3, Kansl1l) have not been functionally defined in heart and/or cardiac disease to our knowledge." (PMID 30241514, 2018).
KANSL1L also shares sentences with these, for which no sentence is quoted: anemia (1 paper); congenital heart disease (1); glioma (1); ovarian carcinoma (1); X-linked deafness (1).